PMP22 (peripheral myelin protein 22)
Diseases named in the same sentence as PMP22 in open-access papers (continued):
Sharing a sentence is not in itself a finding about the gene and the disease.
optic neuritis (2 papers, 2013 to 2025). Optic neuritis is inflammation of the optic nerve, the nerve that carries the visual signal from the eye to the brain.The conditionmay cause sudden, reduced vision in the affected eye(s). "In a recent case report of a CMT1A patient exhibiting recurrent optic neuritis episodes, the authors highlight the putative role of PMP22 overexpression in the development of CNS inflammation, by characterizing peripheral T-cell responses to a panel of myelin epitopes expressed in the CNS." (PMID 24455342, 2013).
ovarian carcinoma (2 papers, 2021 to 2025). A malignant neoplasm originating from the surface ovarian epithelium. "The low expression of ANP32E, STAT1, GPRC5A, EGFL6, and PMP22 was positively associated with overall survival time of ovarian cancer." (PMID 34660776, 2021). "Combining TCGA ovarian cancer dataset, we identified differentially expressed marker genes that were significantly associated with prognosis of ovarian cancer, including ANP32E, STAT1, GPRC5A, EGFL6, PMP22, FBXO21, and CYB5R3." (PMID 34660776, 2021). "We found that the expression of BANF1, CDK2AP2, DDT, LRIG1, MRPL4, and S100A13 was upregulated in ovarian cancer samples, and the expression of EPS8, NUCB2, PAF1, PMP22, RABGAP1L, and USO1 was upregulated in normal samples." (PMID 41000388, 2025). "Furthermore, marker genes, STAT1, ANP32E, GPRC5A, and EGFL6, were highly expressed in ovarian cancer, while PMP22, FBXO21, and CYB5R3 were lowly expressed in ovarian cancer." (PMID 34660776, 2021). "Furthermore, PMP22, FBXO21, and CYB5R3 expression was significantly lower in ovarian cancer tissues compared with normal tissues." (PMID 34660776, 2021). "Studies on the role of PMP22 in the regulation of ovarian cancer have not been reported." (PMID 34660776, 2021).
sensory ataxia (2 papers, 2024). Any ataxia in which the causes of the disease is a perturbation of the sensory system, leading to its dysfunction. "Indeed, a case report of a severely affected PMP22-null boy described predominantly large fiber sensory loss, with decreased proprioception and sensory ataxia." (PMID 38378628, 2024).
Yuan-Harel-Lupski Syndrome (2 papers, 2018 to 2022). "Large duplications that encompass both the PTLS region at 17p11.2 and PMP22 have been reported, and the resulting clinical phenotype is termed Yuan-Harel-Lupski syndrome (YUHAL)." (PMID 29329513, 2018).
adrenomyeloneuropathy (1 paper, 2013). An adult form of the peroxisomal disease X-linked adrenoleukodystrophy (X-ALD), characterized by spastic paraparesia and often associated with peripheral adrenal insufficiency in males.
Anisocoria (1 paper, 2016). Anisocoria, or unequal pupil size, may represent a benign physiologic variant or a manifestation of disease. "Furthermore, anisocoria [PMP22, MPZ, MFN2, SH3TC2; FYVE, RhoGEF, and PH domain‐containing protein 4 (FGD4) gene], miosis (PMP22, MPZ) and mydriasis (MPZ) have been described previously." (PMID 27088055, 2016).
Anxiety (1 paper, 2021). Intense feelings of nervousness, tension, or panic often arise in response to interpersonal stresses. "We showed for the first time a behavior profile trait associated with anxiety and a differential expression of pmp22/PMP22 in hippocampal neurons of TrJ/+ and +/+ mice, demonstrating the involvement at the central level in an animal model of peripheral neuropathy (CMT1E)." (PMID 33921657, 2021). "We explored the expression and localization of pmp22 in some brain areas related to anxiety, such as the hippocampus." (PMID 33921657, 2021). "Therefore, the aim of this study was to determine both the behavior profiles of TrJ/+ and +/+ mice in anxiety tests and the molecular expression of pmp22 in the hippocampus." (PMID 33921657, 2021).
Autoimmunity (1 paper, 2013). The occurrence of an immune reaction against the organism's own cells or tissues.
bladder cancer (1 paper, 2011). "On the other hand, the expression levels of Pmp22 in BBN-induced bladder cancer group were significantly decreased as compared with normal or BBN + nicotinamide-treated groups (P = 0.02 and P = 0.03 by two sample t-test respectively)." (PMID 22028816, 2011).
bladder tumor (1 paper, 2011). "On the other hand, Pmp22 expression level in normal bladder group was significantly higher than in the BBN-induced mouse bladder tumor group." (PMID 22028816, 2011).
brain tumour (1 paper, 2023). "Several negatively correlated genes, including FGF9, ARMCX1, PMP22, and ZBTB18 are involved in nervous system functions, such as glial cell growth, axon regeneration, myelin development and brain tumour suppression." (PMID 37077524, 2023).
breast tumors (1 paper, 2010). "In a retrospective multicenter study, gene expression of PMP22 and the EMPs was measured in 249 primary breast tumors by real-time PCR." (PMID 21159173, 2010).
Cerebellar atrophy (1 paper, 2021). Cerebellar atrophy is defined as a cerebellum with initially normal structures, in a posterior fossa with normal size, which displays enlarged fissures (interfolial spaces) in comparison to the foliae secondary to loss of tissue. "However, there was no statistically significant cerebellar atrophy in the other genotypes (PMP22 duplication, MFN2, or GJB1 mutation)." (PMID 34768465, 2021).
Charcot-Marie-Tooth neuropathies (1 paper, 2025). "The most frequent genetic neuropathies were Charcot-Marie-Tooth neuropathies (CMT) (n = 134), especially CMT1A (n = 89), which is associated with the duplication of the PMP22 gene or a mutation in this gene." (PMID 40883749, 2025).
deafness (1 paper, 2016). An inherited or acquired condition characterized by the complete loss of the ability to hear from one or both ears. "Accordingly, early disturbances of cranial nerves have been described and proposed as the cause of symptoms like deafness in some patients with PMP22 mutations." (PMID 27749933, 2016).
dilated cardiomyopathy (1 paper, 2015). Cardiomyopathy which is characterized by dilation and contractile dysfunction of the left and right ventricles. "LVHT, dilated cardiomyopathy, left bundle branch block, and heart failure may be associated with Charcot-Marie-Tooth hereditary neuropathy type 1A due to the PMP22 duplication on chromosome 17p11.2-12." (PMID 26180644, 2015).
dystrophinopathies (1 paper, 2022). "HNPP resulting from PMP22 gene deletion is a clinical disorder with mild symptoms and generally does not affect the carrier’s quality of life, as in the case of the proband in our study; however, the proband decided to abort the male fetus considering the potential risk of dystrophinopathies." (PMID 36360209, 2022).
endometrial cancer (1 paper, 2011). Primary or metastatic malignant neoplasm involving the endometrium (mucous membrane that lines the endometrial cavity). "In order to investigate the function of PMP22 in endometrial epithelial cells, we monitored PMP22 expression in a panel of endometrial cancer cell lines." (PMID 21518455, 2011).
facioscapulohumeral muscular dystrophy 2 (1 paper, 2023). Any facioscapulohumeral muscular dystrophy in which the cause of the disease is a mutation in the SMCHD1 gene. "Each of these three CNVs contained one likely causative disease gene: SMCHD1, PMP22, or MTM1, involved in facioscapulohumeral muscular dystrophy-2 (digenic inheritence with the D4Z4 permissive haplotype), Charcot-Marie-Tooth disease 1A, and X-linked myotubular myopathy, respectively." (PMID 36781956, 2023).
hereditary spastic paraplegia (1 paper, 2015). Hereditary spastic paraplegias (HSP) comprise a genetically and clinically heterogeneous group of neurodegenerative disorders characterized by progressive spasticity and hyperreflexia of the lower limbs. "The PMP22 duplication is the most common cause of CMT; spinal muscle atrophy is mostly caused by deletions in the SMN1 gene and deletions of SPAST have been identified in hereditary spastic paraplegia." (PMID 25648254, 2015).
lipodystrophy (1 paper, 2017). A congenital or acquired disorder characterized by abnormal loss or redistribution of the adipose tissue in the body. "The common duplication of PMP22 was ruled out by clinical-grade testing, and genes known to cause lipodystrophy (LMNA, PPARG, EMD, AGPAT2, BSCL2) were also sequenced." (PMID 28050599, 2017).
melanoma (1 paper, 2016). A malignant, usually aggressive tumor composed of atypical, neoplastic melanocytes. "Meanwhile, HLA-DRA, INHBA, DKK1, CTGF, PMP22, FLRT3 and NRCAM genes, upregulated in G10, were described as overexpressed in invasive melanomas." (PMID 27206673, 2016).
microphthalmia (1 paper, 2022). Congenital or developmental anomaly in which the eyeballs are abnormally small. "The degree of microphthalmia was paralleled by EtOH dose-dependent reductions in eye and brain BDNF levels (ELISA) and PMP22 expression (FACS), and by dramatic increases in brain (FACS), and eye caspase-3 activity (FACS)." (PMID 36613580, 2022).
mononeuropathies (1 paper, 2025). "In contrast, deletion leads to HNPP through PMP22 haploinsufficiency, producing unstable, thin myelin that's vulnerable to mechanical stress, causing transient, recurrent mononeuropathies." (PMID 41179108, 2025).
neurofibroma (1 paper, 2019). An intraneural or extraneural neoplasm arising from nerve tissues and neural sheaths. "We show that Pmp22 expression decreases significantly in Nf1−/− neurofibroma SCs and increases after Runx1/3 knockout or RUNX1/3-Pmp22–binding site deletion in mouse neurofibroma SCs." (PMID 31032403, 2019). "Western blot verified that the PMP22 protein expression increased in these Ro5-3335–treated mouse neurofibromas compared with vehicle controls." (PMID 31032403, 2019). "Knockdown of Pmp22 with short hairpin RNAs increased Runx1fl/fl;Runx3fl/fl;Nf1fl/fl;DhhCre tumor-derived sphere numbers and enabled significantly more neurofibroma-like microlesions on transplantation." (PMID 31032403, 2019). "We overexpressed Pmp22 in mouse neurofibroma SCs to further determine the role of Pmp22 on SC growth." (PMID 31032403, 2019). "It is plausible that overexpression of Runx1/3 leads to low levels of PMP22 protein expression; therefore, P2 is used more to drive PMP22 protein expression in other tissues during neurofibroma formation." (PMID 31032403, 2019). "We identified peripheral myelin protein 22 (Pmp22/Gas3) related to neurofibroma initiation." (PMID 31032403, 2019). "All these possibilities highlight the need for dynamic PMP22 protein analysis in neurofibroma SCs." (PMID 31032403, 2019). "Conversely, overexpression of Pmp22 in mouse neurofibroma SCs decreased cell proliferation." (PMID 31032403, 2019). "Overexpression of PMP22 in mouse neurofibroma SCs decreases cell proliferation." (PMID 31032403, 2019). "Thus, we identified a signaling pathway involving RUNX1/3 suppression of Pmp22 in neurofibroma initiation and/or maintenance." (PMID 31032403, 2019). "PMP22 expression in neurofibroma may result in alternative availability of the glial PMP22 protein during the cell cycle, leading to aberrant regulation of cell growth control during neurofibromagenesis." (PMID 31032403, 2019). "We also showed that pharmacological inhibition of RUNX/CBFB activity significantly reduced mouse neurofibroma growth in vivo, implicating a novel signaling pathway involving RUNX1/3 repression of Pmp22 in neurofibroma initiation and/or maintenance." (PMID 31032403, 2019). "We found decreased gene expression on the SC differentiation/myelination markers (PMP22, MPZ, and MBP) in both mouse and human plexiform neurofibromas versus WT nerve controls." (PMID 31032403, 2019).
paraplegia (1 paper, 2021). Complete paralysis of the lower half of the body including both legs, often caused by damage to the spinal cord. "Moreover, treatment of JP18/JY13 mice displaying a very severe disease phenotype and paraplegia by siRNA PMP22-SQ NPs resulted in a significant improvement in motor activity." (PMID 33750896, 2021).
peroneal atrophy (1 paper, 2021). "Using whole-exome sequencing and electrophysiological test, we identified a novel insertion mutation of PMP22 (NM_153322, c.54_55insGTGCTG, p.(L19delinsVLL)) in a 26-year-old male patient with peroneal atrophy and nerve conduction was not elicited in electromyography (EMG) study." (PMID 33726003, 2021).
protein misfolding disorders (1 paper, 2015). "Induction of chaperones provides a potential therapeutic approach for protein misfolding disorders, such as peripheral myelin protein 22 (PMP22)-associated peripheral neuropathies." (PMID 25694550, 2015).
Renal cyst (1 paper, 2022). A fluid filled sac in the kidney. "Other signals overlapped Mendelian disorder regions, suggesting variable expressivity and broad impact of these loci, as illustrated by signals mapping to Rotor syndrome (SLCO1B1/3), renal cysts and diabetes syndrome (HNF1B), or Charcot-Marie-Tooth (PMP22) loci." (PMID 35240056, 2022).
sarcoma (1 paper, 2019). A usually aggressive malignant neoplasm of the soft tissue or bone. "We also found that EWS/ATF1-induced sarcoma cell lines express several Schwann cell marker genes such as P75NTR, S100b, Mbp, Plp1, and Pmp22 in vitro." (PMID 31488818, 2019).
urothelial carcinoma of the (1 paper, 2022). "EMP3 belongs to the peripheral myelin protein 22-kDa (PMP22) gene family as novel therapeutic targets in human cancer, which is the most important indicator of progression-free and metastasis-free survival for patients with urothelial carcinoma of the upper urinary tract." (PMID 35492358, 2022).
uveal melanoma (1 paper, 2016). A melanoma derived from melanocytes of the uveal tract.
Vertigo (1 paper, 2024). An abnormal sensation of spinning while the body is actually stationary. "A 22-year-old man, diagnosed with CMT disease by point mutation of peripheral myelin protein 22 (PMP22, c.319+1G>T), visited the emergency room with rotatory vertigo lasting for 24 hours." (PMID 39533607, 2024).
viral infection (1 paper, 2019). "The interaction of SCMV-6K2 with PMP22 might interfere with the biogenesis, or at least with the function of peroxisomes, to suppress the production of ROS, thereby facilitating viral infection." (PMID 31398864, 2019).
peripheral neuropathy (50 papers, 2009 to 2026). A disorder affecting the peripheral nervous system. "We next conducted mechanistic studies to explain why heterozygous expression of T118M PMP22 is disease predisposing but is incompletely penetrant and results in, at most, only mild peripheral neuropathy." (PMID 36581210, 2023). "The progress of molecular genetics has shown that the genetic changes of the PMP22 gene, including duplication, deletion, and point mutation, are behind various hereditary peripheral neuropathies." (PMID 36217151, 2022). "CMT type 1 is an adult peripheral neuropathy commonly caused by duplication mutations in the myelin-associated PMP22 gene." (PMID 35326504, 2022). "In this transgenic mouse, tetracycline administration in adult animals, when Pmp22 overexpression had already caused the peripheral neuropathy, was able to ameliorate the disease with a partial correction of hypomyelination." (PMID 34573256, 2021). "Mutant forms of PMP22 are known to traffic even less efficiently than WT, consistent with the notion that peripheral neuropathies associated with these PMP22 variants also are the consequence of defects in PMP22 trafficking." (PMID 33933451, 2021). "CMT type 1A (CMT1A) is a peripheral neuropathy caused by duplications or mutations in peripheral myelin protein 22 (PMP22), a tetra-span membrane protein." (PMID 32116502, 2020). "Overexpressed PMP22 in Schwann cells due to its duplication in CMT1A patients has been generally thought to be the cause of peripheral neuropathy including demyelination in affected patients." (PMID 31713617, 2020). "Transgenic rodents harboring multiple copies of Pmp22 revealed that aberrant Pmp22 expression is linked with CMT1A-associated peripheral neuropathy whereas heterozygous knockout of Pmp22 resembled some aspects of HNPP." (PMID 31713617, 2020). "With genetic testing becoming more readily available, genetic variants such as T118M in PMP22 should be considered in patients presenting with idiopathic painful peripheral neuropathy." (PMID 30675404, 2018). "This study supports the notion that the T118M variant of the PMP22 gene can be a partial loss of function variant to possibly lead to a disease state marked by painful peripheral neuropathy and certain CMT features." (PMID 30675404, 2018). "This case series supports the argument that the T118M variant of the PMP22 gene can be a partial loss of function mutation to possibly lead to a disease state marked by painful peripheral neuropathy." (PMID 30675404, 2018). "Disturbances in PMP22 are associated with abnormal myelination in a range of inherited peripheral neuropathies both in mice and humans." (PMID 28503382, 2017). "The 81 CMT families had previously been screened for the PMP22 duplication and point mutations in 51 peripheral neuropathy genes, and a genetic cause was identified in 37 CMT families (46%)." (PMID 25648254, 2015). "In fact, aggregation of PMP22 has been proposed to be causal for the demyelination phenotype in the J trembler mouse model of human peripheral neuropathy." (PMID 23750273, 2013). "Increase of pmp22 transcription causes peripheral neuropathy, Charcot-Marie-Tooth disease type1A (CMT1A)." (PMID 19534778, 2009). "The analysis of the pathological mechanisms of the peripheral neuropathies contributed to associating PMP22 function with the structure, sheath formation, maintenance, and stability of the myelin, and with the reduction of internode capacitance to facilitate saltatory nerve conduction." (PMID 35327648, 2022). "For instance, decreases in PMP2, whose mutations can cause demyelinating Charcot–Marie–Tooth disease (CMT) is sufficient to modify the lipidome of peripheral myelin, while heterozygous loss of Pmp22, causing human peripheral neuropathy, disrupts myelin junctions in mice." (PMID 28243725, 2017). "It has been speculated whether other rare CNVs could cause peripheral neuropathies after discovering 17 unique CNVs at the PMP22 locus in CMT patients." (PMID 25648254, 2015).